ABCD3 (ATP binding cassette subfamily D member 3)
Diseases named in the same sentence as ABCD3 in open-access papers (continued):
Sharing a sentence is not in itself a finding about the gene and the disease.
Hepatosplenomegaly (2 papers, 2016 to 2024). Simultaneous enlargement of the liver and spleen. "The transport of branched-chain fatty acids from cytosol to peroxisome is specifically driven by ABCD3, dysfunction of which causes severe liver diseases such as hepatosplenomegaly." (PMID 39223112, 2024). "Recently, it is reported that ABCD3 and ABCD4 are responsible for hepatosplenomegaly and vitamin B12 deficiency, respectively." (PMID 27766264, 2016).
Hypertension (2 papers, 2022 to 2023). The presence of chronic increased pressure in the systemic arterial system. "The independent variables included age > 60 years, history of hypertension, coronary heart disease, ABCD3 score > 6 points, degree of vascular stenosis, and rCBF ≤ 0.8205 as the independent variables." (PMID 37745657, 2023).
ischemic stroke (2 papers, 2014 to 2022). A stroke disorder caused by obstruction of blood flow to the brain, due to thrombotic (local blood clot formation) or embolic (due to a blood clot or other material traveling from another site) event. "The aim of this study is to analyze the ability of ABCD2 and ABCD3 scores to predict ipsilateral ischemic stroke among patients with symptomatic 50-99% carotid stenosis." (PMID 25433667, 2014). "We analyzed if the risk of ipsilateral ischemic stroke differed between various cut-offs for ABCD2 and ABCD3 scores." (PMID 25433667, 2014). "The aim of this study is to analyze the ability of the ABCD2 and ABCD3 scores to predict recurrent ipsilateral ischemic stroke among patients with symptomatic 50-99% carotid stenosis." (PMID 25433667, 2014). "We analyzed the risk of recurrent ipsilateral ischemic stroke before carotid endarterectomy based on each parameter of the ABCD2 and ABCD3 scores separately, and for total ABCD2 and ABCD3 scores." (PMID 25433667, 2014). "The evaluated ABCD2-, ABCD3-score and SPI-II, which all stratify the risk for ischemic stroke after TIA, were not predictive for ipsilateral vascular pathologies or the need for invasive treatment in our study." (PMID 34980008, 2022).
neuroblastoma (2 papers, 2008 to 2024). Neuroblastoma (NB) is the most common solid, extracranial childhood tumor. "A parallel analysis was conducted in the human neuroblastoma cell line SH-SY5Y, wherein peroxisomes were stained with α-ABCD3 (ATP Binding Cassette Subfamily D Member 3)." (PMID 39801517, 2024).
Alzheimer disease (1 paper, 2023). A progressive, neurodegenerative disease characterized by loss of function and death of nerve cells in several areas of the brain leading to loss of cognitive function such as memory and language. "Except for one study analysing ABCD3-positive peroxisomes in neurons of the frontal neocortex of Alzheimer disease (AD) patients, no data on other brain regions or peroxisomal proteins are available." (PMID 37170361, 2023).
benign parotid tumors (1 paper, 2021). "Interestingly, the lower overexpression of ABCD3 in our malignant MEC and ACC tissue compared to PMA, a tumor of benign nature, may suggest a metabolic shift to alternative pathways during malignant transformation of benign parotid tumors." (PMID 34360635, 2021).
biliary atresia (1 paper, 2020). A rare, biliary tract disease characterized by progressive obliterative cholangiopathy of the intra- and extrahepatic bile ducts, occurring in the embryonic/ perinatal period, leading to severe and persistent neonatal jaundice and acholic stool. "Notably, ABCG2 and ABCC4 are almost absent in controls but abundant in biliary atresia; ABCB1 and ABCB4 are both significantly upregulated to the point that ABCB4 is the most abundant transporter in BA Livers, overtaking ABCD3." (PMID 33128234, 2020).
brain tumors (1 paper, 2022). "Firstly, we compared the mRNA expression of ABCD3 in clinical brain tumors with different WHO-classified degrees in the TCGA database." (PMID 35959373, 2022).
cerebral infarction (1 paper, 2023). An ischemic condition of the brain, producing a persistent focal neurological deficit in the area of distribution of the cerebral arteries. "In our study, an ABCD3 score > 6 was used as the cut off value, and we found that an ABCD3 score > 6, rCBF ≤ 0.8205, and the degree of vascular stenosis were all independent risk factors for the progression to cerebral infarction within 90 days of TIA." (PMID 37745657, 2023). "The results demonstrated that ABCD3 score > 6, degree of vascular stenosis, and rCBF ≤ 0.8205 were independent risk factors for cerebral infarction in TIA patients within the 90-day follow-up period, with statistical significance (p < 0.05)." (PMID 37745657, 2023). "Furthermore, rCBF ≤ 0.8205, degree of vascular stenosis, and ABCD3 score > 6 were identified as independent risk factors for secondary cerebral infarction in TIA patients within 90 days in TIA patients." (PMID 37745657, 2023). "Receiver operating characteristic (ROC) curves were generated to evaluate the predictive value of relative cerebral blood flow (rCBF), degree of vascular stenosis, ABCD3 score, and the WB-CTP-ABCD3 combined model for secondary cerebral infarction after TIA." (PMID 37745657, 2023). "Additionally, we propose that combining these WB-CTP findings with the ABCD3 score can enhance the predictive ability for secondary cerebral infarction in TIA patients within 90 days." (PMID 37745657, 2023). "This study aims to assess the predictive value of the combined ABCD3 score and WB-CTP in predicting secondary cerebral infarction in patients with TIA within 90 days in TIA patients." (PMID 37745657, 2023).
glioblastoma multiforme (1 paper, 2022). "The protein expression level was also upregulated in glioblastoma multiforme in comparison with normal tissues based on the data from the CPTAC, indicating that ABCD3 protein and mRNA expression levels were similar in different databases." (PMID 35959373, 2022).
hepatocellular carcinoma (1 paper, 2021). A malignant tumor that arises from hepatocytes. "Based on a series of investigations, it was found that miR-30b-5p may participate in the peroxisome signal transduction by downregulating ABCD3-mediated module 1, thereby promoting the development and progression of hepatocellular carcinoma." (PMID 34651050, 2021). "We also found that miR-30b-5p, an essential gene affecting hepatocellular carcinoma, may contribute to the development and progression of hepatocellular carcinoma by targeting ABCD3-mediated module 1 involvement in the peroxisome signal transduction." (PMID 34651050, 2021).
Hypercholesterolemia (1 paper, 2019). An increased concentration of cholesterol in the blood. "There were significant differences in sex, systolic and diastolic blood pressure, hypercholesterolemia and smoking history, motor weakness, speech abnormalities, acute antithrombotic treatment, and the scores of ABCD2, ABCD3, ABCD3-I, and Dawson between the two groups (P < 0.05)." (PMID 31379718, 2019).
influenza (1 paper, 2018). An acute viral infection of the respiratory tract, occurring in isolated cases, in epidemics, or in pandemics; it is caused by serologically different strains of viruses (influenzaviruses) designated A, B, and C, has a 3-day incubation period, and usually lasts for 3 to 10 days. "One such example of altered gene expression related to lipid and peroxisomal metabolism during influenza, was also revealed in our study, i.e., ABCD3." (PMID 30487780, 2018).
liver cancer (1 paper, 2019). An epithelial or non-epithelial malignant neoplasm that arises from the liver. "To test if Ceapin treatment affects ABCD3 activity, we measured bile acid levels in a liver cancer cell line (HepG2) after Ceapin treatment and ABCD3 KD." (PMID 31149896, 2019).
multiple sclerosis (1 paper, 2023). A progressive autoimmune disorder affecting the central nervous system resulting in demyelination. "The peroxisome proliferator phenylbutyrate reversed the inflammation-induced decrease in ABCD3/PMP70, PEX11β and catalase protein levels and is recommended as a possible drug for treatment of multiple sclerosis." (PMID 37170361, 2023).
parotid tumor (1 paper, 2021). "Indeed, we found a characteristically higher expression of ABCD3 in parotid tumor cells compared to their healthy counterpart, suggesting an enhanced lipid trafficking across peroxisomes." (PMID 34360635, 2021).
renal carcinoma (1 paper, 2020). A carcinoma arising from the epithelium of the renal parenchyma or the renal pelvis.
tumor (11 papers, 2012 to 2025). "Intriguingly, there is a significant increase in PMP70 protein levels in tumor tissues of CRC patients with higher T stages, while the mRNA levels of ABCD3 do not show a similar elevation." (PMID 40229252, 2025). "Many studies have confirmed that ABCD3 plays an important role in the development and progression of many tumors and involves several regulatory mechanisms in tumor development." (PMID 35959373, 2022). "CIBERSORT and Tumor Immune Estimation Resource (TIMER) were also used to investigate the correlation between ABCD3 and cancer immune infiltrates." (PMID 35959373, 2022). "In contrast, in ACC and MEC, ABCD3 seems to be expressed to a lesser extent in tumor than in healthy tissue." (PMID 34360635, 2021). "The roles of high and low levels of expression of ABCD3 vary among different tumor cells." (PMID 40620061, 2025). "ABCD3 was highly expressed in PMA tumor tissue compared to healthy tissue." (PMID 34360635, 2021). "Hence its oncogenic role in tumor development and progression, must be extensively investigated and ABCD3 should be investigated and validated as potential biomarker that can distinguish indolent tumors from those that will go on to become metastatic." (PMID 25802834, 2015). "Clinical evidence showed that ABCD3 mRNA and protein levels are reduced in CRC tumor tissues, and low ABCD3 mRNA levels are correlated with poor prognosis in CRC patients, suggesting a potential tumor-suppressive role for PMP70 in CRC." (PMID 40229252, 2025). "Finally, interrogation of TCGA data sets revealed that the expression of the peroxisome marker ABCD3 and UGCG was also positively correlated with CD36 expression in other tumor types, suggesting that combined inhibition of peroxisomes and UGCG may have broader clinical utility." (PMID 37616051, 2023).
cancer (7 papers, 2013 to 2025). A tumor composed of atypical neoplastic, often pleomorphic cells that invade other tissues. "Among them, high expression of the Abcd3 gene has been shown to be associated with apoptosis and the occurrence of some cancers." (PMID 39061849, 2024). "SCP2, ABCD3, and MICOS10 were significantly negatively correlated with cancer‐associated fibroblasts (CAFs)." (PMID 40620061, 2025). "The mean abundances for ABCD3 are consistent with this reported downregulation in cancer (Liver Set 1: 13.2 ± 0.9 pmol·mg−1 microsomal protein; Liver Set 2: 4.1 ± 0.5 pmol·mg−1 microsomal protein)." (PMID 33128234, 2020). "The study of SCP2, ABCD3, MICOS10, GCDH, and MTRF1L genes' immune infiltration and cancer correlation in CRC offers a fresh perspective." (PMID 40620061, 2025). "We further performed Q-RT-PCR to determine the mRNA expression levels of ABCA2, ABCC1, ABCC4, ABCD3, and ABCF2, which are the ABC transporters expressed in all of the skin samples in our semi-quantitative RT-PCR, in normal and cancer skin." (PMID 25505559, 2013). "The expression levels of ABCA2, ABCC4, ABCD3, and ABCF2 in human skin were similar between normal and cancer individuals." (PMID 25505559, 2013). "ABCD3 is a fatty acid-CoA transporter and the ABCF3 protein is a lipid transporter, both of which do not transport cancer drugs." (PMID 40723843, 2025).
infection (7 papers, 2011 to 2023). The state of being infected such as from the introduction of a foreign agent such as serum, vaccine, antigenic substance or organism. "Flow cytometry analysis showed no increase in the expression of ABCD3 following infection with UV irradiated virus." (PMID 28257516, 2017).
neurodegenerative disease (1 paper, 2020). A disorder of the central nervous system characterized by gradual and progressive loss of neural tissue and neurologic function. "Interestingly, ABCD3 is detected only in nondiseased brain microvessel samples, indicating that it may be downregulated in neurodegenerative disease." (PMID 33128234, 2020).
neuromuscular disease (1 paper, 2024). "Independently, analysis using EHdn on the Genomics England data identified two unrelated individuals within a neuromuscular disease cohort with a clinical diagnosis of OPDM with the same ABCD3 expansion as outliers." (PMID 39068203, 2024). "RNA sequencing and analysis from affected muscle tissue, based on normalised gene counts calculated by OUTRIDER, found that ABCD3 expression in the three OPDM individuals was higher compared to cases affected by other neuromuscular diseases and healthy controls." (PMID 39068203, 2024).
ABCD3 also shares sentences with these, for which no sentence is quoted: colorectal cancer (2 papers); diabetes (2); liver disease (2); acne (1); adrenoleukodystrophy (1); amyotrophic lateral sclerosis (1); chronic myeloid leukemia (1); colon carcinoma (1); colon tumor (1); coronary heart disease (1); COVID-19 (1); distal myopathy (1); genetic disorders (1); hypothyroidism (1); inflammatory bowel disease (1); latent infection (1); lung carcinoma (1); malignant glioma (1); malnutrition (1); melanoma (1); non-small cell lung carcinoma (1); osteoporosis (1); peroxisome biogenesis disorder (1); Refsum disease (1); steatosis (1); transient ischemic attack (1); viral infection (1); vitamin B12 deficiency (1); Zellweger syndrome (1).